GATA4 (GATA binding protein 4)
Diseases named in the same sentence as GATA4 in open-access papers (continued):
Sharing a sentence is not in itself a finding about the gene and the disease.
diabetes (17 papers, 2011 to 2024). "Elevated GATA4 expression was previously associated with diabetes-provoked adverse effects and was prevented by N-acetyl cysteine treatment." (PMID 36568083, 2022). "Likewise, Hnf1b, Gata4/Gata6, Pdx1 or Mnx1-deficient mice fail to develop pancreas of normal size and rather develop diabetes." (PMID 39322760, 2024). "LOF in GATA4 and GATA6 are associated with pancreatic agenesis/hypoplasia and diabetes, along with congenital heart abnormalities and several cancers." (PMID 35052457, 2022). "On the other hand, in diabetes-induced cardiac atrophy, a similar phenotype observed in response to Doxo, GATA4 activity is reduced." (PMID 33869297, 2021). "Firstly, the expression of EPHX1 is regulated by various transcriptional factors including GATA4 and HNF4A, two genes implicated in other forms of monogenic diabetes." (PMID 34342583, 2021). "In failing rat hearts, GATA4 levels are markedly reduced and recent evidence indicates that cardiac GATA4 degradation is increased in diabetes." (PMID 22474596, 2012). "Furthermore, pregestational diabetes increased ROS, impaired cell proliferation, and altered Gata4, Gata5 and Vegf-a expression in the fetal heart of diabetic offspring, which were all prevented by NAC treatment." (PMID 24533448, 2014). "We investigated whether the reduction of cardiac GATA4 expression reported in diabetes alters the expression of downstream genes, namely, atrial natriuretic peptide (ANP), B-type natriuretic, peptide (BNP), and α- and β-myosin heavy chain (MHC)." (PMID 22474596, 2012). "A previous study in Italian male children with NDM, specifically PNDM, found a novel missense mutation (p.Arg319Trp) rather than deletions in the GATA4 gene, although the absence of diabetes in a couple of heterozygous relatives shows that a dominant-negative effect is improbable." (PMID 34584998, 2021). "Streptozotocin-induced diabetic rats and H9c2 embryonic rat cardiomyocytes treated with a high concentration of glucose (a D-glucose concentration of 30 mM was used and cells were cultured for 24 hr) were used to examine the effect of hyperglycemia on GATA-4 accumulation in the nucleus." (PMID 21702924, 2011). "Previous studies have found that GATA4 and GATA6 transcription factors in the pancreas play a key role in neonatal diabetes." (PMID 36650523, 2023).
colorectal cancer (16 papers, 2011 to 2024). A primary or metastatic malignant neoplasm that affects the colon or rectum. "Due to its suppressive effects against ovarian and colorectal cancer cell proliferation, GATA4 is considered to act as a potential tumor suppressor gene." (PMID 35976950, 2022). "Transcription factors GATA4 play an essential role in the development and differentiation of the gastrointestinal tract and are suggested to be involved in colorectal cancer development." (PMID 31405379, 2019). "Two genes correspond to more than two of the 139 CpGs, both are well-known tumour suppressor genes: DCC (DCC = Deleted in Colorectal Cancer) and GATA4." (PMID 24934728, 2014). "With regards to GATA4, its upregulation in colorectal cancer cells adapted to acidosis activates the transcription factor NF-kB, an important regulator of oxidative stress responses that elevates cytokine expression, decreasing ROS levels and suppressing apoptosis." (PMID 39456519, 2024). "Interestingly, GATA4 overexpression showed antitumor effects, with inhibited colorectal cancer cell proliferation, migration, and invasion in vitro." (PMID 36588538, 2022). "Loss of GATA4 expression occurs in many cancers, including epithelial ovarian cancer, adrenocortical tumors, hepatocellular carcinoma, and colorectal cancer, indicating that GATA4 may be a tumor suppressor." (PMID 27788486, 2016). "In vitro studies have shown that GATA4 and GATA5 have a tumor- inhibitory effect in colorectal cancer cells." (PMID 36961416, 2023). "The DNA methylation of GATA4 and GATA5 is a common and specific event in colorectal cancer." (PMID 36961416, 2023). "Although we did observe GATA4 to be overexpressed in foetal colon tissue compared with hESCs, its level of mRNA expression in the normal colon tissue adjacent to colorectal cancer samples was surprisingly low, which is why we did not see further underexpression of this TF in colon cancer." (PMID 27562343, 2016).
liver fibrosis (15 papers, 2017 to 2025). "Loss of GATA4 expression in hepatic sinusoidal cells induces liver fibrosis by increased sinusoidal capillarization and enhanced expression of profibrotic and angiogenic factors like PDGF, Sparcl1, Esm1 and Igfbp5." (PMID 39201329, 2024). "This sinusoidal transformation in the fetal liver inhibited homing of hematopoietic stem and progenitor cells into the fetal liver resulting in fatal anemia, while Gata4 deletion in the mature vasculature caused hepatopathy and perisinusoidal liver fibrosis." (PMID 34658910, 2021). "The selection was either based on significant regulation among the list of CEC-associated genes, relation to liver fibrosis [Gata4, Myc, platelet-derived growth factor subunit B (Pdgfb)], or established LSEC angiocrine factors." (PMID 34658910, 2021). "GATA4 is also expressed by hepatocytes, in addition to HSC in rats, and declining GATA4 levels have been associated with liver fibrosis." (PMID 33916518, 2021). "Using Clec4g-iCre/Gata4fl/fl mice with liver endothelial-specific loss of Gata4 late in fetal life, we demonstrated that endothelial GATA4 controls metabolic dysfunction-associated steatohepatitis (MASH)-like perisinusoidal liver fibrosis by preventing a pathogenic switch in angiocrine signaling." (PMID 40810103, 2025). "Previous work by us could show, that loss of LSEC master regulator GATA4 also induced pro-angiogenic Myc in LSECs, to further amplify a pro-fibrotic angiocrine program, including de novo Pdgfb expression, resulting in perisinusoidal liver fibrosis." (PMID 34658910, 2021). "While GATA4 is downregulated in hepatic fibrosis, GATA3 activation leads to HSC activation and fibrogenesis." (PMID 39201329, 2024). "Our previous work demonstrated that Gata4 inactivation in embryonic HSCs, using the G2-Cre line, leads to liver fibrosis, and therefore, this transcription factor is required to maintain the quiescence of embryonic HSCs." (PMID 34699385, 2021). "Here, we aimed to determine the role of GATA4 in HSC deactivation during adult liver fibrosis regression." (PMID 34699385, 2021). "Overexpression of Gata4 in hepatic stellate cells promoted liver fibrosis regression in CCl4-treated mice." (PMID 34699385, 2021). "Using this adenovirus-mediated system we show that inactivation of Gata4 in adult mice caused HSC activation and liver fibrosis." (PMID 34699385, 2021). "Next, we decided to analyze the Gata4 expression pattern in adult HSCs during the development of liver fibrosis and posterior regression in the CCl4-induced liver injury model." (PMID 34699385, 2021). "More importantly, we found that adenovirus-mediated Gata4 overexpression in fibrogenic HSCs induced the regression of liver fibrosis by deactivating aHSCs." (PMID 34699385, 2021). "More recently, it has been reported that specific inactivation of Gata4 in liver sinusoidal endothelial cells (LSECs) using different Cre drivers results in liver fibrosis." (PMID 34699385, 2021). "Our microarray analysis in Gata4-overexpressing LX2 cells revealed a large number of differentially regulated genes related to liver fibrosis." (PMID 34699385, 2021). "Altogether, our results indicate that reactivation of GATA4 converts aHSC into a quiescent phenotype and, consequently, reverses liver fibrosis." (PMID 34699385, 2021). "Furthermore, the loss of GATA-binding protein 4 (GATA4), an essential transcription factor in LSEC development, also directly leads to the loss of fenestrae and liver fibrosis." (PMID 40573288, 2025). "Moreover, it was demonstrated that the presence of GATA-4 is very important to avoid liver fibrosis." (PMID 40630799, 2025). "LSEC-specific GATA4 knockout mice (Gata4LSEC−KO/BL) developing MASH-like liver fibrosis without steatosis via a pathogenic angiocrine switch were included to compare the impact of liver fibrosis versus hepatic steatosis on hepatic melanoma metastasis." (PMID 39875968, 2025).
liver fibrosis (continued). "Research has discovered that reactivation of GATA4 could change aHSCs into a quiescent phenotype and then reverse liver fibrosis." (PMID 37298621, 2023). "To determine whether Gata4 is reexpressed in HSCs during the regression of liver fibrosis, we performed lineage-tracing analysis by crossing the HSC-specific G2-Cre mouse line with ROSA26R-eYFP mice." (PMID 34699385, 2021). "During regression of liver fibrosis, Gata4 was reexpressed in deactivated hepatic stellate cells." (PMID 34699385, 2021). "To test this hypothesis, we evaluated the effect of Gata4 overexpression on liver fibrosis regression in vivo." (PMID 34699385, 2021). "Gata4 is reexpressed in HSCs during regression of liver fibrosis." (PMID 34699385, 2021). "In this work, we show that lack of GATA4 in adult mice caused hepatic stellate cell activation and, consequently, liver fibrosis." (PMID 34699385, 2021). "The expression data in LX2 cells and Gata4-deficient mice suggested that increased HIF2α activity might be associated with HSC activation and liver fibrosis." (PMID 34699385, 2021). "In particular, our data indicate that reactivation of GATA4 in aHSC is crucial to induce the regression of liver fibrosis and, thus, GATA4 may represent a potential therapeutic approach for liver fibrosis." (PMID 34699385, 2021). "Thus, Gata4 overexpression promotes liver fibrosis regression in vivo by deactivating HSCs." (PMID 34699385, 2021). "Recently, we identified GATA4 as a key transcription factor controlling LSEC development and protecting against liver fibrosis." (PMID 40810103, 2025). "Transcription factors other than c-Maf that determine LSEC differentiation, such as GATA4 or ERG, are known to be downregulated in human patients with liver fibrosis and cirrhosis." (PMID 40810103, 2025). "Thus, GATA4 may be an appropriate target for the resolution of liver fibrosis." (PMID 37298621, 2023). "During injury, Gata4 expression is lost in aHSCs but, notably, is reexpressed during the HSC deactivation process that takes place through the regression of liver fibrosis." (PMID 34699385, 2021). "We also demonstrate that GATA4 regulated the expression of the endothelial PAS domain-containing protein 1 gene (EPAS1) and that EPAS1/HIF2α activity in HSCs induces liver fibrosis in mice." (PMID 34699385, 2021). "Here, we show that GATA4 is a critical regulator of adult HSC quiescence and, therefore, plays a fundamental role in liver fibrosis." (PMID 34699385, 2021). "Finally, we show that GATA4 directly repressed EPAS1 transcription in hepatic stellate cells and that stabilization of the HIF2α protein in hepatic stellate cells leads to liver fibrosis." (PMID 34699385, 2021). "Interestingly, these genes showed the reverse expression pattern in the liver tissue of embryos lacking Gata4 specifically in HSCs, confirming that GATA4 regulates the expression of multiple genes involved in liver fibrosis." (PMID 34699385, 2021). "Thus, it is unlikely that the liver fibrosis we observed in Gata4-floxed mice treated with Ad-Cre might be due to inactivation of Gata4 in hepatocytes or LSECs rather than HSCs." (PMID 34699385, 2021). "Notably, these transcriptomic changes are compatible with alterations in the liver following LSEC-restricted Gata4 deletion, which results in sinusoidal capillarization, hepatopathy, and perisinusoidal liver fibrosis without changes in hepatic triglyceride levels." (PMID 33745018, 2021).
pancreatic cancer (15 papers, 2018 to 2025). "The expression of GATA4 and GATA6 are linked to the differentiation level and grading of pancreatic cancer, whereas lower GATA4 and higher GATA6 levels are connected to survival rates." (PMID 40699746, 2025). "GATA4 is a member of GATA transcription factors family that was found to be implicated in pancreatic cancer." (PMID 39103560, 2024). "In gastric and colon tumors, GATA4 has been reported to exhibit tumor-suppressive functions, whereas in ovarian and pancreatic cancers it appears to act in an oncogenic capacity." (PMID 41303462, 2025). "In pancreatic cancer, GATA4 knockdown increased the ability to form colonies in CFPAC-1 cells, while its in vivo overexpression inhibited tumor growth." (PMID 39456519, 2024). "Another study suggested that a high level of GATA4 expression is correlated with the decreased differentiation of pancreatic cancer (p = 0.037)." (PMID 37372326, 2023). "In our experiments, the GATA4 factor demonstrated a decrease in the expression in three out of six pancreatic cancer cell lines (Colo357, MiaPaCa-2, and Panc1) with the downregulated expression of SOX9." (PMID 35884771, 2022). "In our study, we discovered a link between the expression of SOX9 in pancreatic cancer cell lines and the expression of the GATA4 and GATA6 proteins." (PMID 35884771, 2022). "As a transcription factor, GATA4 can regulate the expression of numerous tumor-related genes in pancreatic cancer." (PMID 33648545, 2021). "Consistently, GATA4 knockdown also reversed the inhibition of proliferation and invasion ability of pancreatic cancer cells induced by WDR3 silencing." (PMID 33648545, 2021). "GATA4 mRNA expression is upregulated in pancreatic cancer cell lines and tissues, and downregulation of GATA4 expression increases drug sensitivity in cancer cells." (PMID 33648545, 2021). "Taken together, our results provide new insights into the specific mechanism by which GATA4 regulates the progression of pancreatic cancer." (PMID 33648545, 2021). "We identified a novel mechanism by which WDR3 plays a critical role in promoting pancreatic cancer progression by activating the Hippo signaling pathway through the interaction with GATA4." (PMID 33648545, 2021). "In the context of cancer, GATA4 has been shown to exert context-dependent functions—acting as a tumor suppressor in gastric and colon cancers, while displaying oncogenic behavior in ovarian and pancreatic tumors." (PMID 41303462, 2025). "In pancreatic cancer, differential hydroxymethylation of genes related to pancreas development or function (GATA4, GATA6, PROX1, ONECUT1, MEIS2), and cancer pathogenesis (YAP1, TEAD1, PROX1, IGF1) have also been shown to reliably identify pancreatic cancer from peripheral blood samples." (PMID 36835649, 2023). "In tumors, GATA4 may have variable effects, acting as a tumor suppressor in lung cancer but upregulated in pancreatic cancer." (PMID 38110859, 2023). "Therefore, the regulation of YAP1 by WDR3 was found to be dependent on GATA4 in pancreatic cancer cells." (PMID 33648545, 2021). "Finally, the upregulation of YAP1 expression induced by WDR3 was dependent on an interaction with GATA binding protein 4 (GATA4), the transcription factor of YAP1, which interaction induced the nuclear translocation of GATA4 in pancreatic cancer cells." (PMID 33648545, 2021). "Similarly, GATA4 is also upregulated in pancreatic cancer and other cancers." (PMID 38110859, 2023). "By interacting with GATA4, WDR3 activated the Hippo signaling pathway, demonstrating that it was crucial in promoting the advancement of pancreatic cancer." (PMID 38098990, 2023). "GATA4 knockdown reversed the inhibition of YAP1 and proliferation and invasion of abilities of pancreatic cancer cells induced by WDR3 silencing and reversed the upregulation of YAP1 expression induced by WDR3 overexpression." (PMID 33648545, 2021).
pancreatic cancer (continued). "Interestingly, our results identified a protein interaction between WDR3 and GATA4 that led to the regulation of GATA4 nuclear translocation and YAP1 expression in pancreatic cancer." (PMID 33648545, 2021). "In conclusion, we proved that GATA4, acting as a transcription factor, could transcriptionally upregulate YAP1 expression in pancreatic cancer cells." (PMID 33648545, 2021). "Furthermore, WDR3 induced YAP1 expression by interacting with GATA4 and inducing the nuclear translocation of GATA4, the transcription factor of YAP1, in pancreatic cancer cells." (PMID 33648545, 2021). "Furthermore, WDR3 silencing could significantly decrease the proliferative and invasive abilities of pancreatic cancer cells by inducing YAP1 inhibition, which was found to rely on the interaction between WDR3 and GATA4." (PMID 33648545, 2021). "Similarly, our results indicated that GATA4 could function as a transcription factor to induce YAP1 expression and activate the Hippo signaling pathway, which resulted in pancreatic cancer progression." (PMID 33648545, 2021). "However, PDACs also exhibited a high incidence of amplification or gain of GATA4 and GATA6, suggesting that in certain instances these TFs may confer a growth advantage to pancreatic cancer cells." (PMID 30190481, 2018).